EIF4E (eukaryotic translation initiation factor 4E)
Diseases named in the same sentence as EIF4E in open-access papers (continued):
Sharing a sentence is not in itself a finding about the gene and the disease.
cancer (continued). "Increased eIF4E activity enhances cap-dependent translation of mRNAs with a high degree of secondary structure within their 5' untranslated regions (UTRs), a subset of transcripts greatly enriched for cancer-related messages." (PMID 21320304, 2011). "Next, we wished to examine whether eIF4E activities within tumour cells predict clinical responses to mTOR inhibition in cancer patients, and whether changes in eIF4E activities after treatment reflect these responses." (PMID 21320304, 2011). "Despite these concerns, specifically targeting the eIF4E/eIF4G protein–protein interaction is an attractive therapeutic approach, and subsequent generations of such inhibitors may provide a novel and important way of targeting eIF4E in human cancers." (PMID 21772331, 2011). "This study identified translational regulation of several mRNA targets important for cancer development, and suggested that altered translational control downstream of eIF4E hyperactivation may be required for AKT-driven cellular transformation." (PMID 21772331, 2011). "In addition, nuclear export of some cancer-related transcripts is stimulated by highly active eIF4E." (PMID 21320304, 2011). "In our study the expression of EIF4E was found to be reduced in the early onset group compared to the late onset group, which may indicate that early onset cancers develop in an EIF4E independent manner." (PMID 20459617, 2010). "Thus eIF4E modulates the expression of the downstream effector proteins that regulate processes up regulated in cancer cells like the cell cycle, survival and cell growth." (PMID 19134194, 2009). "As a consequence of this central role, eIF4E is an established target for cancer therapy." (PMID 19367274, 2009). "Here, we have tested the hypothesis that combined analyses of expressions and phosphorylation states of eIF4E, and its regulators allows greater understanding of eIF4E activity and its influence on cancer than examination of eIF4E expression alone." (PMID 19367274, 2009). "Our hypothesis was that the combined analyses of these pathway components would allow insights into eIF4E activity and its influence on cancer." (PMID 19367274, 2009). "Our hypothesis was that combined examination of eIF4E and its regulators would allow greater insights into eIF4E's influence on cancer." (PMID 19367274, 2009). "One might expect a general translational stimulation to result from the increased eIF4E expression in cancers, on account of enhanced mRNA cap recognition, yet effects of eIF4E overexpression are more subtle." (PMID 19367274, 2009). "The results indicated that patients with high eIF4E had a statistically significant higher rate of cancer recurrence (n = 38, p = 0.03 log-rank test) and cancer-related death (n = 38, p = 0.04 log-rank test) compared to those with low eIF4E overexpression in a 40-month follow-up." (PMID 19134194, 2009). "The overlap in mRNA targets coupled to the fact that both eIF4E and HuR are involved in transformation and elevated in human cancers, suggests that eIF4E could be a downstream effector of HuR activity." (PMID 20049173, 2009). "In addition, we also explored the expression of AGO2, EIF4E3, DCPS and EIF4E in pan-cancer." (PMID 37353728, 2023). "Indeed, eIF4E is often expressed at high levels in cancer cells." (PMID 37143925, 2023). "In addition, overexpression of eIF4E will increase the probability of cancer recurrence." (PMID 37601696, 2023). "Accordingly, targeting eIF4E-eIF4A-dependent translation downstream of mTOR enhances the activity of rapamycin and this may be an effective therapeutic strategy to target oncogenic translation programs in cancer." (PMID 36900235, 2023). "Moreover, exo-eIF4E RNA expression in late stage (III + IV) patients was significantly higher than that in early stage (I + II) patients, thus suggesting RNA expression of exo-eIF4E may correlate with cancer progression." (PMID 35158999, 2022).
cancer (continued). "Secondly, as eIF4E overexpression promotes the expression of ERα, with the increasing amount of ERα available in cells, the original tamoxifen dosage might become insufficient to suppress the ER-signalling pathway and inhibit cancer cell growth." (PMID 32066877, 2020). "Hence, overexpression of eIF4E might be a biological marker for malignant tumors, with clinical significance of poor prognoses." (PMID 33489719, 2020). "Therefore, pharmacological and/or genetic blockage of key nodes of the HSP90/AXL/eIF4E/UPR signaling cascade selectively induces apoptotic cell death of drug-resistant cancer cells, limits tumor heterogeneity in vitro, and precludes the emergence of adaptive phenotypes in vivo." (PMID 31431614, 2019). "Cytarabine, an antimetabolic agent currently used for the treatment of AML, was previously shown to induce phosphorylation of eIF4E on serine 209, which could constitute a potential anti-cancer resistance mechanism activated during administration of this therapy." (PMID 31903169, 2019). "In addition, it could lead to hyperactivation of S6K-1, 4EBP1 and eukaryotic translation initiation factor 4E (eIF4E), as well as cancer growth through the activation of lipid and protein biosynthesis." (PMID 31075885, 2019). "However, in about 30% of cancers, elevated eIF4E correlated with a poor prognosis." (PMID 31878201, 2019). "Since cancer cells with high eIF4E expression demonstrate resistance to the anti-proliferative effects of asTORi, combining dual mTORC1 and 2 inhibitors with HSV1-dICP0 could potentially provide the selective advantage of increasing viral oncolysis of mTOR-inhibitor resistant cancer cells." (PMID 30138450, 2018). "Therefore, we hypothesized that dysregulated protein synthesis due to altered eIF4E/4E-BP ratio in cancer cells is responsible for the differences in HSV1-dICP0 infection between normal and cancer cells treated with asTORi." (PMID 30138450, 2018). "Although many reports associated the 4E-BP1/eIF4E axis to the development of different cancers, 4E-BP1 phosphorylation in HCV core transgenic mice was not sufficient to initiate carcinogenesis and thus subsequent oncogenic alterations were required to drive oncogenesis." (PMID 28915586, 2017). "Although we have not specifically investigated these pathways in the present study, it is plausible that targeting AURKA in CDDP‐resistant cancer models may induce cancer cell death not only through the suppression of eIF4E‐c‐MYC‐HDM2, but also through reversing these signaling effects." (PMID 28417568, 2017). "Indeed, several translation initiation factors that are overexpressed in human cancer, including EIF4E, EIF4G, EIF3A, EIF3C, and EIF3H may also contribute to tumorigenesis." (PMID 28594900, 2017). "Therefore, combination of targeting both mTOR signaling and Mnk/eIF4E pathway to enhance mTOR-targeted cancer therapy might be an innovation therapeutic strategy for NSCLC patients." (PMID 27050281, 2016). "eIF4E's role in regulating cell cycle and proliferation in tumor models, together with its integral role in oocyte meiotic cell cycle progression, has made it a popular therapeutic target in cancer treatment studies and enhanced our understanding of cancer cell translational control." (PMID 26357652, 2015). "They showed that prevention or disruption of the activation of Akt and eIF4E enhanced rapamycin-mediated growth inhibition, indicating that the induced activation of Akt and eIF4E survival pathways counteracts the mTOR inhibitor's effect on the growth of human cancer cells." (PMID 26351512, 2015). "In cancer cells, however, 4E-BP1 is frequently hyperphosphorylated by its upstream oncogenic signals such as PI3K/AKT and RAS/RAF/MEK/ERK pathways, which causes 4E-BP1 disassociation from eIF4E and thus inactivates 4E-BP1 function and increases the level of free eIF4E." (PMID 24970798, 2014).
cancer (continued). "To determine whether targeting the Mnk-eIF4E axis in cancer cells is an additional mechanism to CDK9 inhibition or a consequence of CDK9 pathway alteration, we conducted experiments utilizing shRNA-mediated CDK9 inhibition to compare with the pharmacological effects of CDKI-73." (PMID 25277198, 2014). "Finally since eIF4E is over-expressed in various cancers, and is under investigation as a potential drug target, our findings also have major implications for the design and synthesis of potential therapeutic agents targeting the eIF4E protein." (PMID 24086504, 2013). "In addition, HuR regulates expression of eIF4E in cancer cells." (PMID 22666083, 2012). "Thus, in cancer cells, cap complex activation may result from three separate routes: inactivation of 4E-BPs by phosphorylation, upregulation of eIF4E and transcriptional downregulation of 4E-BP1." (PMID 22216185, 2011). "Therefore, we determined the expression levels of eIF4E and its most well-established regulatory proteins 4E-BP1, 4E-BP2 and p4E-BP1 within tumour cells of a large cohort of cancer patients, and have combined these data into an improved measure of prognosis and estimate of eIF4E activity." (PMID 19367274, 2009). "The biological pathways driven by eIF4E and NCBP2 overexpression differed although they both had cancer phenotypes." (PMID 40766477, 2025). "In acute myeloid leukaemia (AML), this interaction between eIF4E and NBS1 plays a pivotal role in activating AKT, which supports cancer cell survival and proliferation." (PMID 41208200, 2025). "Mechanistically, it was reported that BGN secreted by cancer cells was elicited by Akt/mTOR and MNK/eIF4E pathways and offered the immunosuppressive microenvironment to cancer cells by recruiting suppressive myeloid cells." (PMID 40524231, 2025). "An elevated protein expression of EIF4E, EIF4G3, LARP1, METTL1, NCBP1, NUDT4, and NUDT11 was discerned in the carcinoma samples, whereas the WDR4 expression was comparable between the tumor and adjacent non‐tumorous tissues." (PMID 40485623, 2025). "In fact, tumours that have increased EIF4E and low EIF4E3 expression demonstrate that EIF4E3 is of essential inhibitory mechanism that is lost in certain cancers." (PMID 38071502, 2024). "The translation factor eIF4E also cooperates with c-Myc in lymphomagenesis, and the interaction between AKT and eIF4E is significant in oncogenesis and cancer therapy." (PMID 39494346, 2024). "At the molecular level, ZFAS1 binds miR-150-5p, the inhibitor of eIF4E (eukaryotic translation initiation factor 4E), which is required for the translation of several genes involved in proliferation, survival, EMT, and cancer invasion." (PMID 37628760, 2023). "Further, MNK1/2 being at the center of eIF4E signaling and mTORC signaling, pharmacological inhibition of MNK1/2 is a potent strategy to combat various cancers including TNBC." (PMID 37766871, 2023). "The results of pathway analysis have shown that significant cancer-related (AKT/mTOR and c-Met pathways) and translation-related mechanisms (eIF4E release, translation factors) were enriched." (PMID 38072995, 2023). "Hence, targeting eIF4E may be an alternative treatment strategy for live cancer." (PMID 36118897, 2022). "The inhibition of MNKs and the phosphorylation of eIF4E have been found to impair the process of EMT (epithelial-to-mesenchymal transition) and metastasis in cancer cells." (PMID 35877722, 2022). "The most dysregulated genes were related with the signaling pathways such as AKT-MTOR, CYCLIN D1, KRAS, EIF4E, RB, and ATM, which play an essential role in cancer cell proliferation, survival, and response to external stimuli." (PMID 34944712, 2021).
cancer (continued). "They found some analogues in this series to be markedly more potent than the parent prototypic inhibitor in the disruption of EIF4E/EIF4G interaction, and inhibition of human cancer cell proliferation." (PMID 33539648, 2021). "Conversely, several studies suggest that the phosphorylation of eIF4E by MNK1 and MNK2, in response to stimuli, such as stress or mitogens, has direct effects on cancer onset and progression." (PMID 34541613, 2021). "The eIF4E partner protein and RNA export target, CPSF3, has been shown to be a potential target candidate as well as a prognostic biomarker for a multitude of cancers, e.g., AML and Ewing’s sarcoma." (PMID 34944805, 2021). "However, eIF4E may serve as a key translation target for anti-cancer treatment." (PMID 34209750, 2021). "Previous studies typically targeted eIF4E to inhibit EMT and metastasis of cancer cells, because eIF4E is generally overexpressed in multiple cancers." (PMID 34906136, 2021). "The aaRS profiles are compared to genes with established roles in cancer, including a tumor suppressor (RB1), a proto-oncogene (MYC), and a translation factor (eIF4E)." (PMID 33266490, 2020). "We also included genes with well-established roles in cancer, including MYC (proto-oncogene), RB1 (tumor suppressor), and EIF4E (translation initiation factor), to contrast with the aaRS genes." (PMID 33266490, 2020). "We found a similar inhibitory effect of the SRO-91 on the localization of eIF4E, confining it to a perinuclear location, where it might interfere with translation regulation of the molecules involved in the proliferation and survival of cancer cells in the presence of the SRO-91." (PMID 31825993, 2019). "Various studies have documented ribavirin acting via several pathways in cancer cells, including the IMPDH, ERK/MAPK, eIF4E, and EZH2 pathways." (PMID 29487714, 2018). "Here, we focussed on eIF4E, SRSF3, and UNR as examples of RNA regulons involved in cancer progression." (PMID 30455716, 2018). "It was reported that activation of the 4E-BP1/eIF4E axis selectively stimulates the expression of malignancy-related mRNAs and phosphorylation of 4E-BP1 enables cancer cell survival by enhancing protein synthesis capacity." (PMID 28915586, 2017). "Given that 3-AWA inhibits c-FLIP through abrogation of translation initiation by co-targeting mTOR and Mnk-eIF4E, it (3-AWA) can be exploited as a lead pharmacophore for promising anti-cancer therapeutic development." (PMID 26728896, 2016). "Inhibition of Mnk-mediated eIF4E activity is believed to have a major impact on the PI3K/Akt/mTOR and Ras/Raf/MAPK pathways in human cancers." (PMID 25277198, 2014). "Moreover, reducing Mnk/p-eIF4E expression with novel RRs could also provide a therapeutic strategy for the treatment of additional aggressive cancers because Mnk1/2 and eIF4E/p-eIF4E expressions are reported to be up-regulated during progression of all types of solid tumors and hematologic cancers." (PMID 24504069, 2014). "In this section I will introduce a subset of RBPs involved in cancer development which play key roles in each of the steps of RNA regulation, namely, Sam68, eIF4E, La, and HuR to illustrate the powerful RBP regulatory capacity in cancer." (PMID 22666083, 2012). "A subset of the targets (BCL2, CLU, HSPB1, BIRC5, EIF4E and RRM2) is being investigated for cancers in combination with approved cytotoxic drugs." (PMID 22989709, 2012). "Examination of 37 paired tissues of NSCLC tumors and adjacent uninvolved lung, and the NSCLC cell lines for c-Myc, eIF4E and CDK4 expression showed enhanced levels in tumor tissues and cancer cell lines." (PMID 21092188, 2010). "Many cancer-related signalling pathways, including PI3K and p38, converge to regulate eIF4E and 4E-BP phosphorylation; therefore, eIF4E activity seems to be a key cancer-signalling node." (PMID 19367274, 2009).
cancer (continued). "Although these studies are in AML patients, the ability to target eIF4E has clear implications for the development of treatments for HNSCC and other cancers with elevated eIF4E." (PMID 20049173, 2009). "A relation between translational control and malignant cell transformation became obvious, when elevated levels of eIF-4E as well as reduced levels of the eIF-2α kinase, PKR, were detected in cancer cells." (PMID 12085193, 2002). "Moreover, the levels of downstream molecules (including p-eIF4E, cyclin D1, snail, and Bcl2) regulated by RACK1 were also decreased after SENP3 knockdown, which is consistent with the impact of SENP3 on cancer hallmarks." (PMID 39755756, 2025). "Notably, this level of overexpression is in the mid-range of expression seen in eIF4E and NCBP2 overexpression cancers and is thus physiologically relevant." (PMID 40766477, 2025). "This was correlated with reduced cMyc and ZNF598 proteins levels and increased cMyc stalling as indicated by the increased S-cMyc/FL-cMyc ratio, and reduced cMyc target eIF4E level, supporting the relevance of the RQC of stalled cMyc translation in a mammalian cancer setting." (PMID 39161732, 2024). "Several drugs target eIF4E and or the MAPK cascade to treat cancer." (PMID 36994107, 2023). "In addition, we establish the feedback activation of translation of key cancer growth-promoting proteins such as p90-RSK1 and MKNK2 that signals to eIF4E-eIF4A dependent translation following mTOR inhibition." (PMID 36900235, 2023). "Since MNK1/2 are at the crossroads of other signaling pathways vital for the cancer development and progression such as mTORC1-4E-BP1 signaling and eIF4E signaling axes, restraining MNK1/2 significantly inhibits cancer cells proliferation, cell migration, invasion, and metastasis." (PMID 37766871, 2023). "4EGI-1, a small molecular compound targeting to inhibit eIF4E-eIF4G binding, can reduce the expression of c-Myc without affecting the expression of β-actin and has been proved to play an anti-cancer role in human cancer cells without obvious toxicity." (PMID 37601696, 2023). "In this study, we provide evidence that, in cancer cells, EIF4E has an unexpected nontranslational function, rendering malignant cells particularly vulnerable to ferroptosis." (PMID 36274088, 2022). "Many studies characterize the effect of mTOR, oncogenes, EIF4A, and EIF4E on translation; however, the specific effects arising from modulating 4EBP1 on mRNA translation in cancer are not well-defined." (PMID 35626002, 2022). "We briefly elaborate on a non-canonical TLK1 isoform selectively expressed in eIF4E-rich cellular milieu and its role in limiting cancer treatment efficacy." (PMID 35048066, 2021). "Phosphorylation of eIF4E seems to have no functional role under physiological conditions but is an independent prognostic factor in several types of cancer." (PMID 35582305, 2021). "Notably, apart from eIF4E-dependent oncogenic translation, MNK1/2 exert diverse roles in cancer-promoting pathways." (PMID 33564073, 2021). "EIF-4E can affect cancer progression by regulating the translation of a variety of proteins including RAS and cyclin D-MYC, which are closely related to the proliferation, cell cycle regulation and growth of cancer cells." (PMID 34512368, 2021). "It will be interesting to test whether these eIF4E inhibitors potentiate TKI activity in B-ALL and other cancers." (PMID 34737376, 2021). "For those with matched normal tissues (n = 25), we observed a significant increase in eIF4E phosphorylation in the setting of cancer compared with noncancerous urothelium as we have observed in WT BBN-treated mice." (PMID 34032633, 2021). "Furthermore, constitutively activated MNK1 promotes tumor progression in a way similar to eIF4E, and the kinase-inactive MNK mutant suppresses the proliferation of cancer cells in vivo, thus, suggesting the critical role of MNK/eIF4E pathway in tumorigenesis." (PMID 33148274, 2020).